CHIT1 (chitinase 1)
Diseases named in the same sentence as CHIT1 in open-access papers (continued):
Sharing a sentence is not in itself a finding about the gene and the disease.
Obesity (8 papers, 2018 to 2023). Accumulation of substantial excess body fat. "The effect of the most frequent CHIT1 gene variants, the 24 base pair duplication (dup24) and G102S polymorphism, upon the association between circulating CHIT1 activity and the obesity level, was also investigated." (PMID 35806923, 2022). "High CHIT1 activity is also reported in patients with conditions associated with obesity, such as atherosclerosis and non-alcoholic fatty liver disease." (PMID 35806923, 2022). "The BMI-for-age z score significantly (p = 0.031) predicts increased CHIT1 activity in children with overweight, obesity, and extreme obesity after controlling for the two gene variants, age, gender, and time since weight gain." (PMID 35806923, 2022). "Children with overweight, obesity, and extreme obesity who are also heterozygotes for dup24 allele tended to have a lower value of log CHIT1 plasma activity (a decrease by 39.74% in the CHIT1 plasma activity)." (PMID 35806923, 2022). "Validation of the present findings by future investigations with a larger cohort is necessary to acknowledge the effect of the 24-base pair duplication and G102S polymorphism of CHIT1 gene when evaluating CHIT1 activity as an inflammatory marker in children with obesity." (PMID 35806923, 2022). "Our longitudinal analysis found that a significant reduction in the CHIT1 circulating activity co-occurs with a decrease in the insulin resistance, as expressed by the TG/HDLc, in children with obesity." (PMID 36670674, 2023). "Our results suggest that BMI-for-age z score predicts the increase of CHIT1 circulating activity starting from children with overweight to children with extreme obesity after controlling dup24 and G102S genotypes as covariates." (PMID 35806923, 2022). "A significantly higher logCHIT1 plasma activity was found in children with extreme obesity than in children with overweight (p = 0.048 for the uncorrected CHIT1 and 0.026 for the corrected CHIT1)." (PMID 35806923, 2022). "The CHIT1 plasma activity (logCHIT1) and log-transformed CHIT1-corrected plasma activity (logCHIT1-corrected) showed higher values in children with obesity and extreme obesity." (PMID 35806923, 2022). "More specifically, the elevated CHIT1 circulating levels are significantly higher in children with extreme obesity than in children with overweight." (PMID 35806923, 2022). "The increasing CHIT1 activity has been attributed to macrophage activation in adults with obesity-driven complications and in children with glucose intolerance." (PMID 35806923, 2022). "Our results showed that CHIT1 plasma activity increases with the level of obesity in the evaluated children." (PMID 35806923, 2022). "More specifically, the chitotriosidase (CHIT1) circulating levels are significantly higher in children with extreme obesity than with overweight." (PMID 35806923, 2022). "In this study, we constructed a co-expression network between obesity and PTC and identified four common hub genes (MNDA, TNC, CHIT1, MMP9) and two common TFs (ELF4, STAT3), which might provide new diagnostic and therapeutic strategies for obesity-related PTC." (PMID 37671970, 2023). "We hypothesized that CHIT1 circulating activity is a mediator for the relationship between visceral adipose accumulation and insulin resistance in children with obesity." (PMID 36670674, 2023). "Concerning the assessment of insulin sensitivity, gold standard techniques, such as a hyperinsulinemic-euglycemic clamp, might capture more accurately the relationship between CHIT1 circulating activity and insulin resistance in children with obesity." (PMID 36670674, 2023). "We hypothesize that plasma CHIT1 activity, as a marker of low-grade systemic inflammation, might be elevated in children with high levels of obesity." (PMID 35806923, 2022).
Obesity (continued). "We showed that children with normal weight and overweight have a lower circulating CHIT1 activity than children with obesity and extreme obesity, with the significance threshold being achieved when children with overweight were compared to those with extreme obesity." (PMID 35806923, 2022). "Our study aimed to assess whether the CHIT1 circulating activity, as a macrophage activation indicator, reflects the change of the adiposity level and the insulin resistance (IR) in children with obesity." (PMID 36670674, 2023). "Circulating CHIT1 might be an accurate indicator of inflammation in children with obesity." (PMID 35806923, 2022). "In addition to these results, our data indicate that CHIT1 may be a valuable measure for the extent of the adipose tissue inflammation even before obesity-driven complications occur in children." (PMID 35806923, 2022). "Additionally, the attempts to facilitate the measurement of CHIT1 activity through blood spot tests may be an incentive for evaluating it as a screening tool for complications in children with obesity." (PMID 35806923, 2022). "Consequently, our findings may also suggest that CHIT1 activity could be a more sensitive indicator for the initiation of inflammatory processes in children with obesity than the previous markers." (PMID 35806923, 2022). "Similarly, little is known about the relationship between CHIT1 and obesity." (PMID 30311184, 2018). "Association between OSA severity and CHI3L1 levels or CHIT1 activity (independent of or dependent on obesity level) could not be confirmed." (PMID 30311184, 2018). "Association between OSA severity and CHI3L1 levels/CHIT1 activity (independent of or dependent on obesity) could not be confirmed." (PMID 30311184, 2018). "Our results indicate that in the GSE44000 obesity-related dataset, the expression levels of MNDA, TNC, CHIT1, and MMP9 exhibited significant differences." (PMID 37671970, 2023). "The aim of this preliminary study was to evaluate the roles and interaction of OSA severity (AHI, oxygen desaturation index [ODI]), and obesity (BMI) on CHI3L1 levels and CHIT1 activity in a clinical cohort of patients with moderate to severe OSA (AHI ≥ 15)." (PMID 30311184, 2018). "Based on our findings, it can be concluded that these four genes (MNDA, TNC, CHIT1, and MMP9) may have important biological roles in preventing and treating obesity and PTC." (PMID 37671970, 2023). "In conclusion, these four genes (MNDA, TNC, CHIT1, MMP9) may serve as a link between obesity and PTC and should be further examined in subsequent analyses." (PMID 37671970, 2023). "Our results showed that CHIT1 plasma activity increases with the obesity level in our pediatric population without metabolic complications." (PMID 35806923, 2022). "An interaction effect did not appear between PAP treatment and obesity regarding CHIT1, as there were no significant changes in activity after treatment when analyzed by different BMI categories." (PMID 30311184, 2018). "Furthermore, the effect of PAP treatment, degree of obesity, and OSA severity did not associate with CHIT1 activity." (PMID 30311184, 2018). "Obesity and age were independently associated with CHI3L1 levels but not with CHIT1 acitvity." (PMID 30311184, 2018). "Chitinases, chitotriosidase (CHIT1), acidic mammalian chitinase (AMCase or CHIA), and nonenzymatic chitinase-3-like protein 1 (CHI3L1) have been implicated in various pathological conditions, such as Gaucher’s disease (CHIT1), obesity, diabetes, cardiovascular diseases, and asthma (CHIA)." (PMID 35330193, 2022).
lysosomal storage disease (7 papers, 2013 to 2025). A metabolic disorder caused by mutations in proteins critical for lysosomal function, including lysosomal enzymes, lysosomal integral membrane proteins, and proteins involved in the post-translational modification and trafficking of lysosomal proteins. "Samples from patients with Niemann-Pick diseases type C were used as a biomarker benchmark to establish CHIT1 levels in relation to a prototype of a lysosomal storage disease." (PMID 39891741, 2025). "In other lysosomal storage diseases, serum CHIT1 concentrations decreased significantly after ERT initiation." (PMID 39891741, 2025). "Increased plasma CHIT1 levels were also reported in children with immunodeficiency and lysosomal storage disorders." (PMID 35806923, 2022). "The circulating CHIT1 activity is a valuable marker in lysosomal storage disorders (i.e., Gaucher disease type 1)." (PMID 35806923, 2022). "However, in lysosomal storage disorders, macrophages are considered the primary source of serum CHIT1." (PMID 39891741, 2025). "Lysosomal storage disease genes include GRN, GPNMB, GAA, and CHIT1 which, according to STRING analyses, interact with CD68, CD63, and TLR3, and are known to have lysosomal membrane function." (PMID 37422510, 2023).
interstitial lung disease (6 papers, 2016 to 2025). A diverse group of lung diseases that affect the lung parenchyma. "Recent human and preclinical studies demonstrated that CHIT1 plays an important role in the pathogenesis of both IPF and scleroderma-associated interstitial lung disease (SSc-ILD)." (PMID 35370755, 2022).
Stroke (6 papers, 2013 to 2024). Sudden impairment of blood flow to a part of the brain due to occlusion or rupture of an artery to the brain. "In stroke, CHIT-1, TNF-α and other pro-inflammatory cytokines are accepted as markers of microglial activation, occurring independent of pre-existing inflammatory or infectious conditions in patients." (PMID 24295388, 2013). "Finally, CHIT1 has become a marker specific for macrophage activation during the stroke, and its activity correlates with the grade of the stroke." (PMID 34203467, 2021). "Six proteins (AGFG2, C1QTNF1, CHIT1, DNAJC15, FTL, and OLR1) have been reported to be implicated in other neurodegenerative diseases such as AD, ALS, or stroke, but not in PD." (PMID 37422510, 2023). "Although studies report higher CSF CHIT-1 levels in several neurological diseases including MS, AD and stroke, no study till date documents its elevated levels in ALS, where maximum increase was observed compared to other neurodegenerative diseases." (PMID 24295388, 2013).
type 2 diabetes (6 papers, 2015 to 2025). "These authors were the first to demonstrate that the immunomodulatory effects of CHIT1 may be implicated in nephropathy development during Type 2 diabetes." (PMID 35330193, 2022). "CHIT1 has recently been identified as a marker of macrophage activation in chronic kidney diseases and type 2 diabetes mellitus, as well as bronchial asthma." (PMID 41303283, 2025). "Chitinase (CHIT1 activity) was earlier suggested as a marker of Type 2 diabetes because increased CHIT1 activity in serum can serve as a biomarker of inflammation." (PMID 35330193, 2022). "Recently, increased CHIT1 expression in adipose-tissue macrophages was shown in patients with Type 2 diabetes, pointing to the suitability of this metric as a potential biomarker of adipose-tissue inflammation." (PMID 35330193, 2022). "We aimed to determine the levels of neutrophil-derived chitotriosidase (CHIT1), acidic mammalian chitinase (AMCase) and chitinase 3-like protein 1 (YKL-40) in patients with type 2 diabetes (T2D) and verify their association with metabolic and clinical conditions of these patients." (PMID 26517273, 2015). "Correlations of proteins from family 18 of glycosyl hydrolase (CHIT1, AMCase and YKL-40) and leukocyte elastase in neutrophils of patients with type 2 diabetes." (PMID 26517273, 2015). "Nevertheless, there were no aberrations in serum CHIT1 enzymatic activity in the same patients with Type 2 diabetes." (PMID 35330193, 2022).
diabetes (5 papers, 2015 to 2025). "CHIT1 and YKL-40 are not specific to lung pathology and their levels can be elevated in multiple conditions, such as cardiovascular disease, cancer, inflammation, diabetes, and others." (PMID 36497025, 2022). "It seems that levels of neutrophil-derived CHIT1, AMCase and YKL-40 are independent of achievement of metabolic compensation of diabetes and their increase may be related to other biochemical pathways occurring in diabetes." (PMID 26517273, 2015). "It was previously indicated that both CHIT1 and YKL-40 are stored in specific granules of neutrophils in healthy individuals, but there is no information about AMCase, and it is not known how metabolic conditions of diabetes may influence content of these proteins in neutrophilic granules." (PMID 26517273, 2015).
tuberculosis (5 papers, 2013 to 2024). A chronic, recurrent infection caused by the bacterium Mycobacterium tuberculosis. "Due that plasma levels of IL-6, IFN-γ, IL-33, and CHIT1 appear to differentiate severe TB from mild APTB during the first 2 months of anti-tuberculosis treatment, we conducted an analysis using ROC curves to determine the diagnostic accuracy of these molecules, concerning APTB severity." (PMID 38137331, 2023).
bancroftian filariasis (3 papers, 2016 to 2020). "Here, we determined the association of CHIT1 polymorphisms with susceptibility to bancroftian filariasis (BF) in 88 individuals at the Thai–Myanmar border." (PMID 30934653, 2019). "These functions are likely to be related to the resistance to helminths; pertinently, CHIT1 deficient individuals from South India were more susceptible to Wuchereria bancrofti infection, although such protective effect has not been replicated in other studies." (PMID 27977724, 2016). "Data suggest that polymorphisms of CHIT1, contributing inactive CHIT protein, might increase susceptibility to lymphatic filarial parasites.CHIT1 deficiency, due to the polymorphisms, increases the susceptibility to bancroftian filariasis in southern Indian population." (PMID 34621114, 2020).
chitotriosidase deficiency (3 papers, 2019 to 2025). The chitotriosidase gene is assigned to chromosome 1q31-q32. "One patient (Pt 8) was diagnosed with chitotriosidase deficiency – homozygote for the 24 bp-duplication in the CHIT1 gene." (PMID 30795770, 2019). "However, around 6% of the general population have been found to have severe chitotriosidase deficiency, due to the presence of a homozygous 24-base pair duplication in the chitotriosidase gene CHIT1." (PMID 41146229, 2025). "Furthermore, we did not test for genetic variants of the CHIT1 gene (24 base pair duplication), which causes a chitotriosidase deficiency and therefore could be partly responsible for the values below the LLOQ." (PMID 34321067, 2021).
cryptococcosis (3 papers, 2015 to 2022). An acute or chronic, localized or disseminated infection by Cryptococcus neoformans. "Increased Chit1 expression is protective in a murine model of cryptococcosis, and Chit1 is antifungal both in vitro and in vivo." (PMID 35471056, 2022). "A study demonstrates that chitin recognition via CHIT1 promotes harmful T-helper type 2 (Th2) response to cryptococcal infection." (PMID 33468116, 2021). "The importance of Chit1 in promoting Th2 cell-mediated disease in an experimental model of cryptococcosis prompted us to investigate the relevance of chitotriosidase activity in human fungal disease." (PMID 25764512, 2015). "We further showed that chitotriosidase activity was highest in mice and humans infected with C. neoformans, and Chit1 was necessary for efficient Th2 cell induction and disease in our murine model of cryptococcosis." (PMID 25764512, 2015). "The finding suggests that treatments aimed to suppress the detrimental Th2 response by inhibiting CHIT1 maybe necessary to improve progression of Cryptococcosis." (PMID 33468116, 2021).
dementia (3 papers, 2019 to 2025). Loss of intellectual abilities interfering with an individual's social and occupational functions. "Nineteen proteins (20%) were dysregulated in FTD and AD compared to controls, which likely represent general dementia processes (e.g., CHIT1, MMP10, and MMP12)." (PMID 40866991, 2025). "Seventeen proteins had more than a 50% difference between subjects with dementia and controls, including VIM (2.2 fold increase), NTproBNP (2.2 fold increase), CHIT1 (2.2 fold increase), NEFL (1.7 fold increase), ENPP7 (1.6 fold decrease), and FCGR2A (1.5 fold decrease)." (PMID 37175824, 2023). "Our study highlights the changes and potential contributions of several chemokines (CXCL1, CCL3, CXCL5, CXCL6, CCL3, CCL19), interleukins (IL8, IL6-RA, IL18-BP), and other immune markers (OSM, ALCAM, OPG, CHIT1, YKL-40, STAMBP, MMP-9, MMP-10) in the prodromal and dementia phases of AD." (PMID 31694701, 2019).
dyslipidemia (3 papers, 2019 to 2023). "The significant association of TG/HDLc with CHIT1 activity might indicate the capacity of CHIT1 circulating activity in reflecting both dyslipidemia and insulin resistance in the context of visceral tissue inflammation." (PMID 36670674, 2023).
Granuloma (3 papers, 2024 to 2025). A compact, organized collection of mature mononuclear phagocytes, which may be but is not necessarily accompanied by accessory features such as necrosis. "Co‐staining of CD68 and CHIT1 in giant cells subsequently identified CHIT1 as a pure giant cell marker in granulomas of SaM." (PMID 40928208, 2025). "In another single-cell sequencing and spatial transcriptomics study conducted on granulomas from patients with sarcoidosis, CHIT1 expression was found on proinflammatory macrophages in the center of granulomas." (PMID 38785919, 2024). "Among the other differentially expressed genes, notable upregulation of CHIT1 and CHI3L1 is observed in cardiac granulomas." (PMID 40521183, 2025). "CHIT1 was positive on giant cells within granulomas, whereas monocytes were not stained." (PMID 40928208, 2025).
Hepatic fibrosis (3 papers, 2020 to 2024). The presence of excessive fibrous connective tissue in the liver. "The observed significant improvement in inflammation and hepatic fibrosis, particularly at higher doses of the CHIT1 inhibitor, strongly suggests the potential of CHIT1 as a therapeutic target in MASH accompanied by progressive liver fibrosis." (PMID 39381000, 2024). "In the liver, CHIT1 is primarily produced by activated KCs, which activate hepatic stellate cells to induce liver fibrosis." (PMID 35052861, 2022).
Impaired glucose tolerance (3 papers, 2015 to 2023). An abnormal resistance to glucose, i.e., a reduction in the ability to maintain glucose levels in the blood stream within normal limits following oral or intravenous administration of glucose. "Some authors have reported an association of increased CHIT1 activity with impaired glucose tolerance or insulin resistance, but without molecular insight." (PMID 26517273, 2015).
Insulin resistance (3 papers, 2015 to 2023). Increased resistance towards insulin, that is, diminished effectiveness of insulin in reducing blood glucose levels. "Subclinical inflammation, as expressed by the circulating CHIT1 activity, progresses independently of the abdominal adiposity, as measured by the clinical indicators, and is associated with a change in insulin resistance." (PMID 36670674, 2023). "Further research should investigate the molecular mechanisms of insulin resistance concerning the role of CHIT1 and MCP-1 in obese children." (PMID 36670674, 2023). "The mediating role of MCP-1 between the accumulation of macrophages in the adipose tissue and insulin resistance might require an increase in CHIT1 synthesis and its circulating activity." (PMID 36670674, 2023). "Serum CHIT1 activity is reported to predict endothelial dysfunction in patients with newly diagnosed, untreated and uncomplicated T2D, while plasma YKL-40 is related with insulin resistance." (PMID 26517273, 2015).
lung disease (3 papers, 2022 to 2024). "CHIT1 is an enzyme which plays numerous roles in macrophage biology and its increased activity and expression has been implicated in various inflammatory disorders, including lung diseases." (PMID 36902148, 2023). "Inhibition of CHIT1-dependent fibrotic changes in the airways has implications for other lung disorders where profibrotic inflammatory macrophages are progressing disease." (PMID 36902148, 2023).